TPI1 (triosephosphate isomerase 1)
Diseases named in the same sentence as TPI1 in open-access papers (continued):
Sharing a sentence is not in itself a finding about the gene and the disease.
tumor (continued). "Their role in tumor metastasis requires further investigation, but the role may be similar to that of proteins such as TPI-1, ENO1, and TAGLN2." (PMID 23504277, 2013). "Changes of enzyme activity have been reported under normal and pathological conditions, and overexpression of TPI-1 may activate both energy production and protein synthesis/degradation in rapidly growing tumor cells." (PMID 23504277, 2013). "It has been reported that TPI-1 was represented overexpression in tumor cells." (PMID 23504277, 2013). "However, TPI1 was previously proposed as a tumor suppressor gene." (PMID 35509067, 2022). "However, in HCC, TPI1 was identified as a tumor suppressor gene." (PMID 35509067, 2022). "However, LY-294002 reversed TPI1-mediated promotion of tumor formation." (PMID 35509067, 2022). "By stabilizing CDCA5 protein, TPI1 activates PI3K/AKT/mTOR pathway, thereby enhancing tumor progression and glycolysis." (PMID 35509067, 2022). "Previous studies have demonstrated that TPI1 and RAN exerted crucial effects on tumor initiation and progression." (PMID 35836227, 2022). "GPI1, TPI1, GAPDH, PGK1, and PKM2 were consistently upregulated in almost all tumor types, while PCK1, PCK2, and FBP1 were downregulated in tumors." (PMID 35246510, 2022). "TPI1, LDHA, and ENO1 were also found to be frequently upregulated across various tumor types in a prior meta-analysis study." (PMID 32411371, 2020). "Notably, glycolysis enzymes (GPI, LDHA, LDHB, TPI1, and ALDOA) showed specific enrichment in exosomes from the primary tumor." (PMID 38419074, 2024). "Upon knockdown of the metabolic-related genes, direct tumor cell killing was observed for most cell lines and target genes when cultured with T-cells, especially for ALDOA in both luminal and basal-like cells, and TPI1 in luminal cells." (PMID 38714665, 2024). "While the extracellular tumor-linked roles of PGAM1, LDHA, PKM, TPI1, and PGK1 have not been tested, the anti-tumor actions of ALDOA 13, 18, ENO1 16, 18, and GAPDH 20 were reported." (PMID 37056934, 2023). "TPI-1 treatment enhances the number of IFNγ+ cells in mouse and human immune cells and slows tumor growth in immunocompetent mice, but not in athymic nude mice." (PMID 38022587, 2023). "Finally, overexpression of TPI1 increased expression of N-cadherin, vimentin, LDHA, p-mTOR, and CDCA5, whereas reduced E-cadherin in tumor tissues as demonstrated by WB." (PMID 35509067, 2022). "According to IHC from tissue array, TPI1 was expressed in cytoplasmic and nucleus of tumor cells, and significantly higher in BRCA samples than in normal tissues." (PMID 35509067, 2022). "Additionally, four proteins (Triosephosphate isomerase, TPI1; Galectin-3, LGALS3; Galectin-3-binding protein, LGALS3BP; Filamin-A, FLNA) showed average immunostaining in normal tissue and high in tumor tissue." (PMID 32197468, 2020). "Interestingly, we found the tumor promoting function of TPI1 is independent of its enzymatic catalytic activity, but dependent on its translocation to cell nucleus." (PMID 35246510, 2022).
infection (26 papers, 2003 to 2025). The state of being infected such as from the introduction of a foreign agent such as serum, vaccine, antigenic substance or organism. "Similar to other known candidal “moonlighting proteins”, surface-exposed Tpi1 is likely to contribute to fungal adhesion during the colonization and infection of a human host." (PMID 34210257, 2021). "The current study provided structural insights into the interactions of human extracellular matrix proteins with Tpi1 that can occur at the cell surface of Candida yeasts and contribute to the host infection by these fungal pathogens." (PMID 34210257, 2021). "At 48 h post-infection, the up-regulation of triosephosphate isomerase-1 in the fructose and mannose metabolism pathway will increase the level of intracellular Glyceraldehyde-3P, which will accelerate the glycolysis pathway." (PMID 24949634, 2014). "For both species, we again observed the highest Tpi1 exposition on the surface of fungal cells after culturing in RPMI 1640 medium, suggesting a role of this protein in host infection." (PMID 34210257, 2021). "Here, we characterized the binding of candidal Tpi1 to selected human ECM proteins, considering that these interactions are important for the attachment of Candida yeast to host tissues and, consequently, for host infection." (PMID 34210257, 2021).
neurodegenerative disease (6 papers, 2010 to 2024). A disorder of the central nervous system characterized by gradual and progressive loss of neural tissue and neurologic function. "Several proteins were associated with neurodegenerative diseases, DPYSL2 and TPI1 were related to AD, UCHL1 was linked to PD, whereas ALDH was related to AD and PD." (PMID 27857231, 2016).
neurological disease (4 papers, 2012 to 2024). "Some downregulated proteins such as DPYSL2, TPI1, ALDH, and UCHL1 were found to play critical roles in the neurological disease and PSMA1, PSMA3, PSMC2, PSMD11, and UCHL1 in protein homeostasis." (PMID 27857231, 2016).
metabolic disorder (3 papers, 2019 to 2025). "Background and Clinical Significance: Triosephosphate isomerase (TPI) deficiency is a rare autosomal recessive metabolic disorder caused by a pathogenic variant in the TPI1 gene." (PMID 40981120, 2025). "Some genetic mutations of the human TPI1 gene (located on chromosome 12p13.31) have been shown to be associated with metabolic disorders, including a rare autosomal recessive TPI deficiency that presents with severe neurological symptoms and hemolytic anemia." (PMID 39519689, 2024).
TPI1 also shares sentences with these, for which no sentence is quoted: cardiomyopathy (4 papers); genetic disease (4); neuroblastoma (4); osteosarcoma (4); allergic reactions (3); Alzheimer disease (3); autoimmune conditions (3); colorectal cancer (3); parasitic infections (3); allergies (2); aseptic meningitis (2); atherosclerosis (2); bladder squamous cell carcinoma (2); cardiovascular diseases (2); Chagas disease (2); hemoglobinopathies (2); Intellectual disability (2); laryngeal squamous cell carcinoma (2); lung squamous cell carcinoma (2); malaria (2); myopathy (2); skin cutaneous melanoma (2); systemic lupus erythematosus (2); Arthritis (1); asthenospermia (1); asthma (1); atopic dermatitis (1); autoimmune disease (1); bacteremia (1); breast tumors (1).
A further 54 diseases each share a sentence with TPI1 in 1 paper.